RASA4CP (RAS p21 protein activator 4C, pseudogene)
Gene: Transcribed unprocessed pseudogene on chromosome 7 (44,029,334 to 44,041,892, reverse strand). Ensembl gene ENSG00000228903.
Diseases named in the same sentence as RASA4CP in open-access papers:
RASA4CP is named in the same sentence as 2 diseases in open-access papers, as found by Europe PMC text mining. Sharing a sentence is not in itself a finding about the gene and the disease. The quoted sentences say what the papers report.
cervical cancer (1 paper, 2020). A primary or metastatic malignant neoplasm involving the cervix. "Recent study identified a two-lncRNA signature (ILF3-AS1 and RASA4CP) as an independent biomarker which could predict the prognosis of cervical cancer based on the TCGA database and quantitative reverse transcription PCR (qRT-PCR)." (PMID 33328990, 2020).
cancer (1 paper, 2019). A tumor composed of atypical neoplastic, often pleomorphic cells that invade other tissues. "Similarly, the role of RASA4CP in cancer has not been explored." (PMID 31065456, 2019).